PTPN11 (protein tyrosine phosphatase non-receptor type 11)
Diseases named in the same sentence as PTPN11 in open-access papers (continued):
Sharing a sentence is not in itself a finding about the gene and the disease.
breast tumor (12 papers, 2012 to 2023). "For example, knockdown of the protein tyrosine phosphatase SHP2, encoded by PTPN11 in established breast tumors, blocked their growth and reduced metastasis." (PMID 24376839, 2013). "One of the most novel and significant findings of our study is the importance of IL8 and PTPN11 in invasion and intravasation of human breast tumors." (PMID 23113900, 2012). "The promoter analysis of IL1B, CDH13, and PTPN11, using SMART App, showed methylation status in breast tumor patient samples." (PMID 36474139, 2022). "Other genes have been correlated with tumorigenesis, such as CDC25A, PTPN11, and IL8, but have not been extensively studied in regard to migration and invasion of breast tumor cells." (PMID 23113900, 2012).
congenital heart disease (12 papers, 2014 to 2025). A heart disease that is present at birth. "Furthermore, mutations in the PTPN11 gene (encoding protein tyrosine phosphatase Shp2) in families with congenital heart disease have been strongly linked to a high prevalence of hypertrophic heart disease." (PMID 40002810, 2025). "Congenital heart defects (CHD) were seen most frequently in patients with pathogenic variants in exon 3 (28 out of 38 patients) and exon 8 (18out of 28 patients) of the PTPN11 gene see." (PMID 32164556, 2020).
thyroid cancer (12 papers, 2016 to 2024). "With respect to several top genes, like PTPN11, it encodes the protein-tyrosine phosphatase SHP2 whose protein expression was significantly increased in human thyroid carcinoma." (PMID 28155630, 2016). "Besides, PTPN11 was significantly increase expressed in human thyroid carcinoma." (PMID 28938536, 2017).
pulmonary valve stenosis (11 papers, 2007 to 2024). The pathologic narrowing of the orifice of the pulmonary valve. "Most studies have observed that pulmonary valve stenosis is more common in patients with NS who carry a PTPN11 variant." (PMID 39596579, 2024). "Meanwhile, the patient underwent genetic testing given the presence of SNHL and pulmonary valve stenosis, revealing a heterozygous PTPN11 gene with a c.1529A>G variant." (PMID 38515811, 2022). "NS in patients with PTPN11 mutations is more likely be associated with pulmonary valve stenosis or ASD (ostium secundum type)." (PMID 35770001, 2022). "PTPN11 mutations were mainly seen in cases with pulmonary valve stenosis in NS1 patients." (PMID 37529712, 2023). "Six patients had pulmonary valve stenosis or ASD with PTPN11 mutations." (PMID 35770001, 2022). "SOS1 mutations most often result in pulmonary valve stenosis, much like PTPN11 mutations." (PMID 35770001, 2022). "PTPN11-mutation carriers had pulmonary valve stenosis and ASD." (PMID 35770001, 2022). "Notably, in the current investigation, we utilized molecular modeling to examine the molecular mechanism of the detected variant in the PTPN11 gene for pathologies associated with pulmonary valve stenosis, ventricular septal defects, and atrial septal defects." (PMID 36496429, 2022). "Unlike the other two cases, this child received the diagnosis of NS during the first months of life (germline PTPN11 mutation), before developing ALL, because of the presence of typical facial features and pulmonary valve stenosis." (PMID 39336782, 2024). "SOS1, RIT1, PTPN11, and SOS2 mutations showed common cardiac abnormalities such as pulmonary valve stenosis." (PMID 35770001, 2022). "The detected variant in the PTPN11 gene can change the amino acid at position 468 in the PTP domain, hinting at a feasible mechanism for the pathologies associated with pulmonary valve stenosis, ventricular septal defects, and atrial septal defects." (PMID 36496429, 2022). "Among all the pathogenic variants, we found that patients with mutations in RIT1, SOS1, PTPN11, and SOS2 had common echocardiography figures characterized by pulmonary valve stenosis, while RAF1 patients had HCM." (PMID 35770001, 2022). "RIT1, SOS1, PTPN11, and SOS2 had common echocardiography features characterized by pulmonary valve stenosis, while RAF1 was characterized by HCM." (PMID 35770001, 2022).
type 2 diabetes (11 papers, 2013 to 2026). "Related studies indicate that linoleic acid is a multi-target inhibitor of PTPN1, PTPN9, and PTPN11, potentially exerting an anti-diabetic effect to prevent type 2 diabetes." (PMID 41554047, 2026). "Diverse PTPs, such as PTPN1, PTPN2, PTPN9, PTPN11, PTPRS, and DUSP9, have been reported to attenuate insulin signaling and trigger type 2 diabetes, indicating that PTPs are promising drug targets for the treatment or prevention of type 2 diabetes." (PMID 35204821, 2022). "Several protein phosphatases, such as PTPN9, DUSP9, and PTPN11, have been identified as AMPK-related targets for type 2 diabetes." (PMID 35563411, 2022). "Several PTPs, such as PTPN1, PTPN2, PTPN9, PTPN11, PTPRS, and DUSP9, disrupt insulin signaling and trigger type 2 diabetes, indicating that PTPs are promising drug targets for the treatment or prevention of type 2 diabetes." (PMID 35204821, 2022). "Some PTPs, such as PTPN1, PTPN2, PTPN9, PTPN11, PTPRS, and DUSP9, have been shown to attenuate insulin signaling and trigger type 2 diabetes, indicating that PTPs are promising drug targets for the treatment or prevention of type 2 diabetes." (PMID 35204821, 2022). "In previous studies, chebulinic acid was shown to have an antagonistic effect on type 2 diabetes by inhibiting the protein tyrosine phosphatase non-receptor (PTPN)-11 and PTPN9." (PMID 35055051, 2022).
viral infection (11 papers, 2017 to 2024). "PTPN11 (SHP-2, a regulator of cytokine signaling) was elevated in MIS-C, bacterial and viral infection in comparison with KD." (PMID 39300098, 2024).
cardiomyopathy (10 papers, 2007 to 2025). A disease of the heart muscle or myocardium proper. "It was reported that a low dose of dasatinib reversed the expression levels of molecular markers of cardiomyopathy and reduced cardiac fibrosis in NS and LS mice with the PTPN11 mutation." (PMID 32676024, 2020). "We identified novel DNVs in diagnostic-grade genes (RYR2, TNNT2, PTPN11, MYH7, LZR1, NKX2-5), and five cases harbouring a combination of prioritised variants, suggesting that oligogenic inheritance and genetic modifiers contribute to cardiomyopathies." (PMID 36357925, 2022).
cryptorchidism (9 papers, 2016 to 2024). The failure of one or both testes of a male fetus to descend from the abdomen into the scrotum during the late part of pregnancy. "The most frequent clinical manifestations (>60%) in patients with PTPN11 pathogenic variants were a short stature, heart disease, a short neck, pectus excavatum, and cryptorchidism." (PMID 39596579, 2024). "Patient #56, patient #68, patient #79, patient #91, patient #202 and patient #214 all carried mutations in PTPN11; these patients demonstrated different specific facial features, congenital heart anomalies or cryptorchidism." (PMID 37605180, 2023). "44% of male patients with PTPN11 variants were observed to have unilateral or bilateral cryptorchidism." (PMID 32164556, 2020). "Nevertheless, 3 subjects who did not experience delayed puberty had offspring: 2 males carrying heterozygous PTPN11 mutations, 1 of them with cryptorchidism, had children by means of assisted reproductive techniques, and 1 female (RAF1 mutation) had a spontaneously conceived pregnancy." (PMID 39897954, 2024). "Patients with PTPN11 mutation are more likely to have short stature, thoracic malformation, cryptorchidism and mild bruising than those without PTPN11 mutation." (PMID 36760995, 2023). "Among the eighteen genes, four have been previously identified in patients with hypospadias (CYP1A1, FLNA, GLI3, and GLI2), three have been reported to be associated with cryptorchidism (FLNA, RET, and PTPN11), and one has been identified in patients with micropenis (EVC)." (PMID 33424767, 2020).
esophageal cancer (9 papers, 2022 to 2025). A primary or metastatic malignant neoplasm involving the esophagus. "We discovered that PTPN11 was substantially expressed in cholangiocarcinoma (CHOL), colon adenocarcinoma (COAD), esophageal carcinoma (ESCA), head and neck squamous cell carcinoma (HNSC), liver hepatocellular carcinoma (LIHC), and stomach adenocarcinoma (STAD) using the TIMER2 algorithm." (PMID 35802774, 2022).
Osteochondroma (9 papers, 2011 to 2025). A common, benign cartiliginous neoplasm arising from the metaphysis of bone. "One child, who was found to have osteochondroma of the right and left tibia six months after treatment, had growth hormone therapy discontinued, and regular follow‐up was recommended due to the PTPN11 mutation." (PMID 37525886, 2023). "Nevertheless, it is advisable to assess bone metabolism anomalies, especially in children with the PTPN11 pathogenic variant, before administering the medication as well as to monitor scoliosis and osteochondroma during their post‐treatment phase." (PMID 37525886, 2023).
acute leukemia (8 papers, 2011 to 2023). A clonal (malignant) hematopoietic disorder with an acute onset, affecting the bone marrow and the peripheral blood. "Fusion genes have been identified as specific molecular markers of acute leukemia, and PTPN11 mutations have been observed to co-exist with MLL-AML (MLL-AF6, MLL-AF10) and CBFβ-MYH11, which is in accordance with previously reported findings in the literature." (PMID 38025540, 2023). "Fully characterizing how PTPN11 mutations deregulate HSC activity may provide new insights into the pathogenesis of PTPN11 mutation-associated acute leukemias and improve stem cell-based therapies." (PMID 21799948, 2011). "All of the available data support that GOF mutations in PTPN11 play a causal role in NS, LS, and JMML; however, whether the contribution of PTPN11 mutations to acute leukemias represents a primary event or a second hit acquired during disease progression is not conclusive." (PMID 21799948, 2011).
brain tumors (8 papers, 2020 to 2026). "Comparison with published data showed a statistically significant association between brain tumor occurrence and PTPN11-related NS, driven by two genotypes: NM_002834.5(PTPN11):c.182A>G (p.Asp61Gly) and c.417G>T (p.Glu139Asp)." (PMID 41646294, 2026). "We recently identified an accumulation of brain somatic PTPN11 alterations in low-grade epilepsy-associated brain tumors (LEAT), the second largest lesion category in drug-resistant focal epilepsies amenable to neurosurgical treatment." (PMID 36973520, 2023). "We described also a 13-year-old girl with NS associated with a recurrent mutation in PTPN11, who developed three different types of brain tumors, i.e., an optic pathway glioma, a glioneuronal neoplasm of the left temporal lobe and a cerebellar pilocytic astrocytoma." (PMID 32806529, 2020). "The second event was a brain neoplasm (dysembryoplastic neuroepithelial tumor grade 1) reported in a 9-year-old male patient who was PTPN11 positive." (PMID 35245205, 2022). "Although there is no certain relationship between the specific PTPN11 mutation and the incidence of cancer, almost 15% of brain tumors in PTPN11 mutation-associated NS were associated with the heterozygous form of the p.Asn308Asp mutation." (PMID 39336782, 2024).
cartilage tumors (8 papers, 2011 to 2025). "Families with MC segregate heterozygous loss-of-function mutations in PTPN11, and their cartilage tumors are thought to arise from cells that have second-hit somatic PTPN11 mutations." (PMID 24875294, 2014). "However, cartilage tumors can be induced by a conditional biallelic inactivation of Ptpn11, which mimics somatic second-hit PTPN11 mutations that likely give rise to cartilage tumors in human MC patients." (PMID 24875294, 2014). "We previously demonstrated that Ptpn11 gene deletion driven by CD4 Cre recombinase leads to cartilage tumors in a T cell independent manner since the phenotype is observed even in RAG-1 absence." (PMID 34625577, 2021). "Unexpectedly, in aging mice, Ptpn11 gene deletion driven by CD4 Cre recombinase leads to cartilage tumors in wrist bones in a T cell-independent manner." (PMID 29085371, 2017). "PTPN11 deletion in CD4+ cells driven by CD4 Cre recombinase demonstrated that although the ablation of SHP2 does not affect T cell development and functions, it causes cartilage tumors in a T cell-independent manner." (PMID 33777940, 2021). "Unlike humans, cartilage tumors have not been observed in mice that are heterozygous for Ptpn11 loss-of-function mutations, and complete absence of Ptpn11 in mice causes embryonic lethality." (PMID 24875294, 2014). "However, Ptpn11 gene deletion driven by CD4 Cre recombinase leads to cartilage tumors in the wrist." (PMID 34625577, 2021). "Altogether, these data demonstrate that Ptpn11 gene deletion in a non-T cell subset leads to cartilage tumors." (PMID 29085371, 2017). "Surprisingly, in aging mice, Ptpn11 gene deletion driven by CD4 Cre recombinase (but not LckCre) led to cartilage tumors presenting large chondrocyte-like cells and fibrochondrocyte-like cells." (PMID 29085371, 2017). "In 24 percent of the samples we observed heterozygosity for noncoding SNPs that are known common variants, suggesting that large PTPN11 gene deletions and other causes of LOH are not frequently associated with these other cartilaginous tumors." (PMID 21533187, 2011).
cervical cancer (8 papers, 2015 to 2024). A primary or metastatic malignant neoplasm involving the cervix. "Importantly, PTPN11 contributes to the growth and migration of cervical cancer cells and decreases the sensitivity of cells to cisplatin." (PMID 35957898, 2022). "Specifically, PTPN11 facilitates cervical cancer cell proliferation by suppressing interferon-β (IFN-β) production and restricts chemotherapeutic drug-induced apoptosis of cervical cancer cells through Parkin-dependent autophagy." (PMID 35957898, 2022).
deafness (8 papers, 2020 to 2024). An inherited or acquired condition characterized by the complete loss of the ability to hear from one or both ears. "In the course of the experiment, it was found that deep learning was effective in the diagnosis of deafness with PTPN11 gene mutation syndrome." (PMID 36760995, 2023). "In order to remedy this defect, it is of practical significance to study the diagnosis and gene function of deafness caused by PTPN11 gene mutation syndrome." (PMID 36760995, 2023). "Regarding syndromic deafness genes, two de novo variants of PTPN11 were identified in sporadic cases in families 1631 and 1543." (PMID 35248088, 2022). "Herein, we report three patients with NSML among three generations in one family, all presenting with multiple lentigines, HCM and other distinctive clinical and molecular features, including facial dysmorphism, deafness, family history of sudden death and PTPN11 mutations." (PMID 37692036, 2023). "Finally, the gene function of deafness caused by PTPN11 gene mutation syndrome was analyzed, and the conclusion was drawn." (PMID 36760995, 2023). "Gao Y analyzed the clinical phenotype and gene of syndromic deafness with PTPN11 gene mutation." (PMID 36760995, 2023). "The study of PTPN11 gene mutation syndrome deafness was also of great significance in genetics." (PMID 36760995, 2023). "However, there are few researches on the diagnosis and gene function of PTPN11 gene mutation syndrome deafness in the field of deep learning in deafness disease." (PMID 36760995, 2023). "Xu H Y analyzed the relationship between PTPN11 gene and deafness." (PMID 36760995, 2023). "The diagnosis of deafness in PTPN11 gene mutation syndrome has not been studied too deeply at present." (PMID 36760995, 2023).
lymphoma (8 papers, 2015 to 2024). A malignant (clonal) proliferation of B- lymphocytes or T- lymphocytes which involves the lymph nodes, bone marrow and/or extranodal sites. "Therefore, when comparing HS and lymphoma from BMDs, the presence of a PTPN11 mutation was significantly associated with HS (p = 0.0001) based on a two-tailed Fisher Exact Probability Test." (PMID 31277422, 2019). "None of the lymphomas from BMDs had PTPN11 mutations, indicating that within this breed of dogs, this mutation appears to be specifically associated with HS (p = 0.0001)." (PMID 31277422, 2019). "Interestingly, none of the 23 lymphomas from BMDs carried either one of the two PTPN11 mutations studied." (PMID 31277422, 2019). "We did not identify either PTPN11 nor KRAS mutations in any of the lymphoma samples." (PMID 31277422, 2019). "This notion indicated that PLS-123′s great efficacy and anti-proliferative effects in GCB-DLBCL lymphoma might not only be simply attributed to downregulation of BCR signaling pathway alone and alternative selectivity profile provided downregulation of PTPN11 expression should also be considered." (PMID 25944695, 2015).
myeloid leukemia (8 papers, 2014 to 2022). A clonal proliferation of myeloid cells and their precursors in the bone marrow, peripheral blood, and spleen. "Further work must be done to find the importance of having specifically the DNMT3A and PTPN11 genes mutated together, but these are two commonly mutated genes in myeloid leukemia that we have now shown leads to accelerated disease." (PMID 29464054, 2018). "In previous studies, we and other laboratories have reported numerous TET2- and PTPN11-related murine models of myeloid leukemia." (PMID 35771283, 2022). "Because DNMT3A and PTPN11 mutations are found in combination in AML and JMML patients, our double mutant mice provide a novel clinically relevant model for developing and evaluating therapies for myeloid leukemia." (PMID 29464054, 2018). "PTPN11 mutations, which block autoregulation of SHP2 catalytic activity and lead to hyperactivation of RAS/MAPK, JAK/STAT, PI3K/AKT signaling, are responsible for the development of the prosurvival and resistant phenotype in myeloid leukemias and are associated with an overall poor prognosis." (PMID 36460969, 2022). "PTPN11 (SHP2) gain-of-function mutations block autoregulation of SHP2 catalytic activity, leading to uncontrolled hyperactivation of the RAS/RAF/MAPK and JAK/STAT5 pathways, resistance and poor overall survival, which have also been identified in myeloid leukemia." (PMID 36460969, 2022).
psoriasis (8 papers, 2022 to 2025). An autoimmune condition characterized by red, well-delineated plaques with silvery scales that are usually on the extensor surfaces and scalp. "Results showed that the SHP2 coding gene PTPN11 expressed more in the skin from psoriasis patients than from healthy donors." (PMID 35281792, 2022). "Heatmap showed that PTPN11 was positively more correlated with the NF‐κB pathway in macrophages than dendritic cells from psoriasis lesions, suggesting that PTPN11 exacerbates psoriasis mainly in macrophages by activating the NF‐κB pathway." (PMID 34936223, 2022).
pulmonary fibrosis (8 papers, 2017 to 2025). Chronic progressive interstitial lung disorder characterized by the replacement of the lung tissue by connective tissue, leading to progressive dyspnea, respiratory failure, or right heart failure. "Overexpression of constitutively active PTPN11 reduced the responsiveness of fibroblasts to profibrotic stimuli, and viral delivery of PTPN11 to wild-type mice blunted bleomycin-induced pulmonary fibrosis." (PMID 29670881, 2018).